MYD88 (MYD88 innate immune signal transduction adaptor)
Diseases named in the same sentence as MYD88 in open-access papers (continued):
Sharing a sentence is not in itself a finding about the gene and the disease.
mycoplasma pneumonia (4 papers, 2020 to 2024). "This miRNA affects pulmonary inflammatory factors and cell apoptosis in mice with mycoplasma pneumonia by regulating the TLR4/MyD88/NF-κB signaling pathway." (PMID 39328420, 2024). "Upregulation of miR-143-3p expression reduced TNFα, MyD88, p50, and alveolar epithelial cell apoptosis in mycoplasma pneumonia mice by inhibiting TLR4/MyD88/NF-κB axis." (PMID 35812870, 2022). "mRNA and protein expressions of apoptosis-related factors Bax and Bcl-2 were measured by qRT-PCR and Western blot in order to investigate how miR-143-3p mediated TLR4/MyD88/NF-κB signaling pathway to work on the apoptosis of alveolar epithelial cells of mice with mycoplasmal pneumonia." (PMID 32597476, 2020). "The present study aimed to explore the effects of miR-143-3p and Toll-like receptor (TLR) 4/myeloid differentiation factor 88 (MyD88)/NF-κB signaling pathway on pulmonary inflammatory factors levels and alveolar epithelial cell apoptosis in mycoplasmal pneumonia mice." (PMID 32597476, 2020). "We speculated that there might be some miRNAs that could regulate inflammatory cytokine release and alveolar epithelial cell apoptosis in mycoplasmal pneumonia by affecting TLR4/MyD88/NF-κB signaling pathway." (PMID 32597476, 2020). "Therefore, our study was aimed at exploring whether miR-143-3p could affect inflammatory factors’ levels and alveolar epithelial cell apoptosis in mice with mycoplasmal pneumonia by regulating TLR4/MyD88/NF-κB signaling pathway." (PMID 32597476, 2020). "Therefore, up-regulation of miR-143-3p expression may ameliorate pulmonary inflammatory factors levels and reduce alveolar epithelial cell apoptosis in mycoplasmal pneumonia mice by inhibiting TLR4/MyD88/NF-κB signaling pathway." (PMID 32597476, 2020). "Therefore, we speculated that miR-143-3p might regulate MyD88/NF-κB signaling pathway to inhibit inflammatory factors’ levels and alveolar epithelial cell apoptosis in mice with mycoplasmal pneumonia by the targeted down-regulation of MyD88 expression." (PMID 32597476, 2020). "Therefore, we determined that miR-143-3p could negatively regulate MyD88/NF-κB signaling pathway expression in a targeted way, thereby inhibiting the abnormal inflammation and reducing the apoptosis of alveolar epithelial cells induced by mycoplasmal pneumonia in mice." (PMID 32597476, 2020).
neuropathy (4 papers, 2016 to 2025). A disorder affecting the nervous system that manifests with pain, tingling, numbness, and/or muscle weakness. "The involvement of the MyD88-dependent pathway in the PAC-induced neuropathy rat model has been reported." (PMID 36982452, 2023). "MRI, CSF cytology/flow cytometry, and molecular testing, including IGH clonality and MYD88, are central to confirming BNS and distinguishing it from IgM-related neuropathies." (PMID 41154413, 2025). "Biochemical analysis revealed time-dependent upregulation of mRNA and/or protein levels of TLR2 and TLR4 and MyD88 and TRIF adaptor molecules, which was paralleled by an increase in IBA-1/CD40-positive cells under neuropathy." (PMID 26962463, 2016).
neutropenia (4 papers, 2012 to 2023). A decrease in the number of neutrophils found in the blood. "Seven of the hospitalized MyD88- or IRAK-4–deficient patients developed neutropenia during the acute phase of infection (three of four moderate cases and four of six critical cases), whereas only two had a high ANC at a particular time point (ANC > 8,000/mm3)." (PMID 36880831, 2023). "Interestingly, during acute or invasive infections, patients with MyD88 or IRAK-4 deficiency develop neutropenia despite having pus in infected tissues." (PMID 23209417, 2012). "Thus, genetic variants in CARD9- or in MyD88-dependent signaling pathways may predispose to IA only in the setting of innate immune damage (e.g. in patients with neutropenia or in patients that receive corticosteroids)." (PMID 25621893, 2015). "Surprisingly, we observed frequent neutropenia (ANC < 1,500/mm3) in MyD88- or IRAK-4–deficient patients." (PMID 36880831, 2023). "Overall, IRAK-4– and MyD88-deficient patients were able to mount an inflammatory response to SARS-CoV-2 infection, with characteristic neutropenia potentially due to defective IL-1R signaling." (PMID 36880831, 2023).
non-alcoholic fatty liver disease (4 papers, 2022 to 2025). "This study demonstrates that MyD88 in myofibroblasts can promote nonalcoholic fatty liver disease-related hepatocarcinogenesis by enhancing macrophage M2 polarization, which might provide a potential molecular therapeutic target for HCC." (PMID 38291436, 2024). "For instance, in models of non-alcoholic fatty liver disease (NAFLD), combinations of HIIT with L. rhamnosus consistently yielded synergistic suppression of key inflammatory mediators (TLR4, MYD88, NF-κB) and improved lipid markers." (PMID 40822484, 2025).
osteosarcoma (4 papers, 2015 to 2024). A usually aggressive malignant bone-forming mesenchymal neoplasm, predominantly affecting adolescents and young adults. "In vitro experiments validated CD36 and MYD88's roles in promoting osteosarcoma cell proliferation, invasion and migration, emphasising their therapeutic potential." (PMID 38742843, 2024). "Osteosarcoma cell migration was also abolished after treatment with ST2825 suggesting that MyD88 plays a major role in increasing the proliferation rate and reducing apoptosis." (PMID 37749630, 2023). "A recent paper found Toll-7 dependence of RVFV induced autophagy in Drosophila and MyD88 dependence in a human osteosarcoma cell line, although the role of these pathways in human primary immune cell autophagy or immune responses remains unclear." (PMID 25756647, 2015). "The rationale for focusing on CD36 and MYD88 as therapeutic targets is underpinned by studies that demonstrate their involvement in tumorigenic processes and their specific impact on inflammasome regulation, which can significantly influence the progression and aggression of osteosarcoma." (PMID 38742843, 2024). "First, the authors detected the expressions of MyD88, TRIF and NF-κB in vascular walls of 46 patients with TAO and 32 patients with trauma and osteosarcoma by western blot assay." (PMID 38640750, 2024).
plague (4 papers, 2014 to 2023). Plague is a severe bacterial infection caused by the gram-negative bacterium Yersinia pestis. "We compared the proliferative response of splenocytes from wild-type and Myd88 deficient mice vaccinated with the plague vaccine and saw close to a twofold decrease in proliferation between these two groups (P = 0.0425)." (PMID 24995344, 2014). "To characterize the role of MyD88 in primary pneumonic plague, we challenged wild-type C57BL/6 (WT) and Myd88−/− mice by intranasal infection with Yersinia pestis CO92." (PMID 30642901, 2019). "Severity scoring of the liver and spleen showed pronounced differences between WT and Myd88−/− mice at the end stage of plague, with significantly reduced severity in Myd88−/− mice." (PMID 30642901, 2019). "In this work, in order to better understand these observations and the role of inflammation in pneumonic plague, we characterized pulmonary Y. pestis infection of Myd88−/− mice." (PMID 30642901, 2019). "The later hyperinflammatory phase is partially MyD88 dependent and ineffective in the lungs but controls systemic infection and reduces the progression of secondary septicemic plague." (PMID 30642901, 2019). "MyD88 appears to be involved in multiple aspects of the immune response to the plague vaccine and protection against plague infection." (PMID 24995344, 2014). "Nevertheless, Myd88−/− mice were more sensitive to lethality from secondary septicemic plague." (PMID 30642901, 2019). "Further, it may be that part of the reason for the lack of protection against plague in Myd88 deficient mice was possibly a combination of a suboptimal antibody response to the vaccine and attenuated cell-mediated immune responses that led to the inability to clear the pathogen from the mouse." (PMID 24995344, 2014). "In contrast, the dissemination and subsequent development of secondary septicemic plague are not exacerbated by the MyD88 response, and in fact, it is protective against disseminated infection." (PMID 30642901, 2019). "In the murine plague model, TLR7 was a significant contributor to the expression of serum IFN-β, whereas MyD88 was not." (PMID 28847850, 2017). "Interestingly, the current research has found that during Yersinia pestis infection, TLR 7 might have an unconventional signal transduction adapter independent of MyD88, which induces IFN-Is production, inhibiting inflammation caused by the plague." (PMID 38124132, 2023).
Primary Sjögren's Syndrome (4 papers, 2019 to 2024). "Hanying Mei found that total glucosides of paeony can reduce the inflammatory response in mice with Sjogren’s syndrome by regulating the activity of TLR4/MyD88/NF-κB signaling pathway and play an anti-inflammatory role." (PMID 39664524, 2024).
Respiratory tract infection (4 papers, 2012 to 2023). An infection of the upper or lower respiratory tract. "The phenotype of LysM-Myd88−/− mice was very similar to the previously documented phenotype of Myd88−/− mice during Klebsiella pneumonia, underlining the importance of myeloid cell MyD88 during respiratory tract infection." (PMID 25254554, 2014). "Several MyD88 dependent TLRs are known to be important for the innate immune response to respiratory tract infection with K. pneumoniae, particularly TLR4 and TLR9, and during late stage infection or in the presence of high bacterial numbers, TLR2." (PMID 25254554, 2014). "Future studies are warranted to investigate the role of MyD88 and TLR9 in asplenic animals during respiratory tract infection caused by the pneumococcus." (PMID 22721450, 2012). "We also found that IL-21/IL-21R may exacerbate neutrophilic inflammation by modulating the TLR/MyD88 signaling pathway during C. muridarum respiratory tract infection." (PMID 37628738, 2023). "During respiratory tract infection different MyD88 expressing cells may contribute to host defense, including innate immune cells, such as alveolar macrophages, intraepithelial dendritic cells and migrated leukocytes, and parenchymal cells, such as lung epithelium and endothelium." (PMID 25254554, 2014). "Probiotic treatment significantly upregulates the expressions of TLR7, MyD88, IRAK4, TRAF6, and NF-κB to alleviate FM1 influenza virus-induced respiratory tract infection." (PMID 33924002, 2021).
retinal degeneration (4 papers, 2021 to 2024). Degeneration of the retina. "Furthermore, neuroprotection from inhibiting MyD88 in the rd10 mouse model of retinal degeneration was associated with increased microglia/macrophage expressing the Arg1 neuroprotective marker and altered levels of several anti‐inflammatory cytokines." (PMID 34562309, 2021). "There is only limited research on TLR associations in inherited retinal degenerations, although inhibition of the TLR/MyD88 axis has been shown to improve the cell survival." (PMID 38983565, 2022). "In a mouse model of inherited retinal degeneration, inhibition of MyD88 has been shown to reduce the photoreceptor apoptosis and functional loss." (PMID 38983565, 2022). "In this study, we used isobaric tags for relative and absolute quantification (iTRAQ) labelling followed by LC‐MS/MS for quantitative proteomic analysis on the rd10 mouse model of retinal degeneration to identify protein pathways changed by MyD88 inhibition." (PMID 34562309, 2021). "We recently demonstrated that inhibiting MyD88 in mouse models of retinal degeneration led to increased photoreceptor survival, which was associated with altered cytokines and increased neuroprotective microglia." (PMID 34562309, 2021). "Future work will determine whether induction of crystallins by MyD88 inhibition occurs in other tissues or is limited to retinal degeneration, whether the effect persists during the course of injury, and will determine the mechanism of upregulation." (PMID 34562309, 2021). "The purpose of this study was to characterize and quantify early protein changes after MyD88 inhibition in order to gain insight into how blocking MyD88 signalling may lead to photoreceptor protection in the rd10 mouse model of retinal degeneration." (PMID 34562309, 2021).
sarcoidosis (4 papers, 2016 to 2025). Sarcoidosis is a multisystemic disorder of unknown cause characterized by the formation of immune granulomas in involved organs. "MYD88 -938C>A has also been previously associated with sarcoidosis." (PMID 28127112, 2016).
splenic marginal zone lymphoma (4 papers, 2014 to 2026). Splenic marginal zone lymphoma is a rare, indolent B-cell non-Hodgkin lymphoma characterized by abnormal clonal proliferation of mature B-lymphocytes with involvement in the spleen, bone marrow and, frequently, the blood. "Specific oncogenic mutations in the Toll/IL-1 receptor (TIR) domain of MyD88 are found in 91% of lymphoplasmacytic lymphomas, 29% of ABC DLBCL, 9% of gastric MALT lymphomas, 13% of splenic marginal zone lymphomas (SMZL), 2.9% of CLL cases and 5.6% of IgH-mutated CLL cases." (PMID 25112836, 2014). "MYD88 and MYC abnormalities are rarely reported in splenic marginal zone lymphoma (SMZL), and their role in immune dysregulation and transformation remains unclear." (PMID 41756269, 2026). "However, as in the L.CD40 tumor model and in spleen marginal zone lymphomas, the PD1/PD-L1 axis is most likely playing a role in the immune escape of aggressive tumor B-cells with MYD88 activation." (PMID 34017329, 2021).
Splenomegaly (4 papers, 2012 to 2018). Abnormal increased size of the spleen. "We tested for the occurrence of splenomegaly and intrahepatic granuloma formation, and determined the MyD88-independent IFN-αβ response as a measure of LPS sensitivity." (PMID 22745710, 2012).
staphylococcus aureus infection (4 papers, 2007 to 2022). An infectious process in which the bacteria Staphylococcus aureus is present. "They showed that the clearance of Staphylococcus infection in chimera mice reconstituted with IL-1R-deficient or Myd88-deficient BM was the same." (PMID 21857913, 2011). "MyD88-deficient mice also mount a normal host defense response to Staphylococcus aureus infection." (PMID 17615075, 2007). "Here, we show that MPLA-induced resistance to Staphylococcus aureus infection is lost in MyD88-KO, but not TRIF-KO, mice." (PMID 36439136, 2022).
status epilepticus (4 papers, 2018 to 2025). Status epilepticus is defined as a continuous seizure lasting more than 30 min, or two or more seizures without full recovery of consciousness between any of them. "Another study also indicated that inhibition of MyD88 signaling shifted microglia polarization from M1 to M2 phenotype and attenuated neuronal apoptosis in the hippocampus of mice after status epilepticus." (PMID 32206297, 2020). "Inhibition of MyD88 signaling attenuates neuronal death in the hippocampus after status epilepticus in mice by skewing microglia/macrophage polarization." (PMID 31866829, 2019).
Streptococcus pneumonia (4 papers, 2011 to 2025). "Children that lack MyD88 signaling develop pyogenic infections, primarily due to Streptococcus pneumonia, and individuals with CARD9 deficiency develop mucocutaneous and disseminated candidiasis and dermatophytosis." (PMID 25621893, 2015).
ZIKV infection (4 papers, 2018 to 2024). "Following ZIKV infection, AaNRP robustly recruited virus-permissive myeloid cells, some of which some became infected and released new infectious virus, resulting in more efficient virus dissemination and worse infection in a MyD88 pathway-dependent manner." (PMID 38499785, 2024). "Since the TLR signaling pathway has been shown to induce the autophagy pathway via adaptor proteins MyD88 or TICAM, we next investigated a potential link between TLR3 and the autophagy pathway in the context of ZIKV infection and pathology." (PMID 30735502, 2019). "Our data show that ZIKV infection induces the expression of TLR2, TLR3, and adaptor molecule MYD88." (PMID 30781519, 2019).
acute respiratory distress syndrome (3 papers, 2021 to 2025). Progressive and life-threatening pulmonary distress in the absence of an underlying pulmonary condition, usually following major trauma or surgery. "Both myeloid differentiation primary response 88 (MyD88) and TRIF sorting adaptors have been implicated in the proliferation of acute respiratory distress syndrome caused by other respiratory viruses." (PMID 34211370, 2021). "The alternative splicing of MyD88 and IRAK1 has been examined in a cohort of patients with Acute Respiratory Distress Syndrome (ARDS)." (PMID 36531997, 2022).
alcohol use disorder (3 papers, 2019 to 2023). "These two pro-inflammatory families play an important role in the neurobiology of alcohol use disorder, specifically MyD88 regulates ethanol drinking, ethanol-induced sedation, and ethanol-induced deficits in motor coordination." (PMID 31817854, 2019).
alcoholic fatty liver disease (3 papers, 2016 to 2024). Lipid infiltration of the hepatic parenchymal cells that is due to alcohol abuse. "Using alcoholic fatty liver disease model, we consistently revealed that MyD88 in HSCs promotes hepatic adipogenesis and inflammatory responses via OPN secretion." (PMID 38291436, 2024). "Moreover, berberine diminished inflammation and lowered the levels of TNF-α, IL-6, and IL-1β in rats with non-alcoholic fatty liver disease by regulating the TLR4/MyD88/NF-κB signaling pathway." (PMID 38790653, 2024).
allergic rhinitis (3 papers, 2023 to 2024). Inflammation of the nasal mucous membranes caused by an IgE-mediated response to external allergens. "A recent research found that miR-224-5p overexpression has the potential to inhibit the TLR4/MyD88/NF-κB pathway, thus reducing the ovalbumin-induced allergic rhinitis-associated inflammatory response and thereby limiting allergic rhinitis." (PMID 39421730, 2024). "These compounds alleviate allergic rhinitis symptoms by inhibiting inflammatory mediators, oxidative stress, apoptosis, and key signaling pathways such as MAPK/NFκB and TLR4/MyD88/NF-κB." (PMID 39403140, 2024).
antibody deficiency (3 papers, 2022 to 2025). "These primary immunodeficiencies included antibody deficiencies, complement defects (C2 or C3), congenital asplenia, and signaling defects in MYD88 and IRAK4." (PMID 41510457, 2025). "Apart from antibody deficiency, differential diagnostic considerations should include complement deficiency, asplenia or splenic impairment as in sickle cell disease, and defects in innate immunity such as Toll-like/IL1R defects e.g., IRAK4/MyD88 deficiency." (PMID 38933494, 2024). "If any of these mechanisms, including complement or antibody deficiency, problems in the TLR signaling cascade (such as MYD88 or IRAK4 mutations), or congenital asplenia, are lacking in children, they are at a higher risk of recurrent or severe IPD." (PMID 41510457, 2025).
aspergillosis (3 papers, 2010 to 2015). Aspergillosis is an infection, growth, or allergic response caused by the Aspergillus fungus. "Conversely, bolstering MyD88 signaling in dendritic cells improves resistance to aspergillosis." (PMID 26367276, 2015). "In humans, Mendelian defects in MyD88 and CARD9 signaling do not lead to the spontaneous development of aspergillosis, unlike individuals with Mendelian defects in NADPH oxidase activity (i.e. chronic granulomatous disease)." (PMID 25621893, 2015).